METTL18 (methyltransferase 18, RPL3 N3(tau)-histidine)
Description:
Protein-L-histidine N-tele-methyltransferase that specifically monomethylates RPL3, thereby regulating translation elongation. Histidine methylation of RPL3 regulates translation elongation by slowing ribosome traversal on tyrosine codons: slower elongation provides enough time for proper folding of synthesized proteins and prevents cellular aggregation of tyrosine-rich proteins.
Synonyms: AsTP2; C1orf156; MGC9084; HPM1
Tractability: No criterion of Open Targets' tractability assessment is met for any kind of drug.
Gene: Protein-coding gene on chromosome 1 (169,792,529 to 169,794,991, reverse strand). Ensembl gene ENSG00000171806.
Subcellular location: Cytoplasm, cytosol; Nucleus; Nucleus, nucleolus
Subcellular location (Human Protein Atlas): Nucleoplasm; Cytosol
Gene Ontology:
Molecular function: heat shock protein binding; protein binding; protein-L-histidine N-tele-methyltransferase activity
Biological process: peptidyl-lysine monomethylation; regulation of ribosome biogenesis; regulation of rRNA processing; regulation of translation; regulation of translational elongation
Cellular component: cytosol; nucleolus; nucleus; protein-containing complex
Genetic constraint (gnomAD): Loss-of-function variants: 16 observed, 21.78 expected, observed/expected ratio (o/e) 0.73, 90% interval 0.5 to 1.12. The upper end of that interval is the gene's LOEUF score, 1.12, which puts it in group 4 of 6, group 1 being the genes least tolerant of losing a copy. Missense variants: 392 observed, 440.72 expected, observed/expected ratio (o/e) 0.89, 90% interval 0.82 to 0.97. Synonymous variants: 131 observed, 153.8 expected, observed/expected ratio (o/e) 0.85, 90% interval 0.74 to 0.99.
Homologues: Orthologues: chimpanzee METTL18 (99% identical), macaque METTL18 (95% identical), pig METTL18 (82% identical), dog METTL18 (81% identical), guinea pig METTL18 (78% identical), rabbit METTL18 (77% identical), rat Mettl18 (70% identical), mouse Mettl18 (69% identical), tropical clawed frog mettl18 (45% identical), zebrafish mettl18 (38% identical), Drosophila melanogaster CG17219 (29% identical), Caenorhabditis elegans metl-18 (23% identical).
Diseases named in the same sentence as METTL18 in open-access papers:
METTL18 is named in the same sentence as 8 diseases in open-access papers, as found by Europe PMC text mining. Sharing a sentence is not in itself a finding about the gene and the disease. The quoted sentences say what the papers report.
breast carcinoma (1 paper, 2024). "The biphosphorylated Src had kinase activity similar to the conventional active form of the Src kinase; therefore, we argue that biphosphorylated Src is a crucial pathogenic molecule related to HER2-negative breast cancer with high METTL18 expression." (PMID 39309445, 2024). "Interestingly, the expression of METTL18 was increased in HER2-negative breast cancers, and this increase was associated with the upregulation of p-Src." (PMID 39309445, 2024). "The association between METTL18 and metastasis was further investigated using the database of patient samples from the Metastatic Breast Cancer Project (Provisional cBioportal, Metastatic Breast Cancer Project)." (PMID 39309445, 2024). "A gene expression comparison of 31 METTL series genes and 22 methyltransferases in breast cancer patients revealed that METTL18 is highly amplified in human HER2-negative breast cancer." (PMID 39309445, 2024). "In conclusion, we demonstrated that the generation of biphosphorylated Src by a METTL18-driven RPL3/HSP90/actin/Src sequential pathway significantly contributes to the metastasis of HER2-negative breast cancer." (PMID 39309445, 2024). "In breast cancer tissue from the Samsung cohort, phosphorylated-Src levels consistently correlated with METTL18 expression." (PMID 39309445, 2024). "Taken together, these results support the critical role of METTL18 in the metastatic response of HER2-negative breast cancer cells." (PMID 39309445, 2024). "METTL18 was abundantly expressed in patients with HER2-negative breast cancer with metastases." (PMID 39309445, 2024). "Interestingly, METTL18 knockdown affected p-Src levels only in MBA-MB-231 cells and not in SK-BR3 or MDA-MB-453 cells, indicating that Src regulation by METTL18 is limited to HER2-negative breast cancer." (PMID 39309445, 2024). "However, the mRNA expression levels of Src remained unchanged in breast cancer, suggesting that METTL18 regulates Src at the post-translational level." (PMID 39309445, 2024). "Therefore, Src regulation via METTL18 suppression is expected to be a good strategy for HER2-negative breast cancer therapy." (PMID 39309445, 2024). "However, the role of METTL18 in breast cancer remains unknown and requires further study." (PMID 39309445, 2024). "Like METTL18, survival probability was diminished in HER2-negative breast cancer patients exhibiting heightened phosphorylation of Src at Y419." (PMID 39309445, 2024). "To elucidate the biological role of METTL18, we compared the mRNA expression level of METTL18 with 30 other METTL series genes and 22 methyltransferases using TCGA data, which are classified by breast cancer subtype." (PMID 39309445, 2024). "The METTL18 gene showed a breast cancer subtype-specific expression distribution, with high amplification in HER2-negative breast cancer patients." (PMID 39309445, 2024). "The enhanced HSP90 observed in HER2-positive breast cancer does not seem to be a decisive factor contributing to the oncogenic potential of METTL18." (PMID 39309445, 2024). "Therefore, we propose METTL18 as a valuable target molecule for the inhibition of metastasis and improvement of survival in HER2-negative breast cancer patients who receive no benefit from conventional drugs." (PMID 39309445, 2024).
Breast Invasive Carcinoma (1 paper, 2024). "In comparisons of protein levels utilizing a dataset from Breast Invasive Carcinoma (TCGA PanCancer Atlas), we consistently found a correlation between the protein levels of METTL18 and HSP90." (PMID 39309445, 2024).
breast tumor (1 paper, 2024). "Loss of METTL18 significantly reduced the metastatic responses of breast tumor cells in vitro and in vivo." (PMID 39309445, 2024). "Therefore, in this study, we examined the role of METTL18 as a crucial component of metastatic responses by breast tumor cells and carefully dissected the underlying mechanisms involved in Src regulation by METTL18." (PMID 39309445, 2024).
hepatocellular carcinoma (1 paper, 2021). A malignant tumor that arises from hepatocytes. "Firstly, to better evaluate the significant role of METTL18 in progression of hepatocellular carcinoma, all types of clinical characteristics should be involved, for example, the way of treatment for each patient." (PMID 34123827, 2021). "Furthermore, the impact of METTL18 on the ability of proliferation, invasion, and migration of hepatocellular carcinoma cells was explored in vitro." (PMID 34123827, 2021). "Moreover, we further knock down the expression of METTL18 in vitro to detect the impact on the ability of proliferation, invasion, and migration of hepatocellular carcinoma cells." (PMID 34123827, 2021). "Methyltransferase-like 18 (METTL18), a METTL family member, is abundant in hepatocellular carcinoma (HCC)." (PMID 34123827, 2021).
liver cancer (1 paper, 2021). An epithelial or non-epithelial malignant neoplasm that arises from the liver. "Based on our study, the expression levels and prognostic values of METTL18 were evaluated, we found that expression of METTL18 is abnormal in a number of tumors and significantly high in liver cancer in multiple databases." (PMID 34123827, 2021). "In addition, METTL18 expression values in 50 tumor samples were significantly higher than 50 paired normal samples in the TCGA database via analyzing the expression of METTL18 in liver cancer, (P < 0.001)." (PMID 34123827, 2021). "Therefore, our results reveal the potent modulating role of METTL18 in immune response with liver cancer." (PMID 34123827, 2021).
cancer (2 papers, 2021 to 2024). A tumor composed of atypical neoplastic, often pleomorphic cells that invade other tissues. "In this study, we explored the biological function of METTL18 in cancer metastasis and dissected the molecular mechanisms underlying METTL18-mediated tumorigenic responses." (PMID 39309445, 2024). "A very recent study revealed that METTL18 is a histidine methyltransferase that regulates translation in cancer cells." (PMID 34285249, 2021). "The TCGA Pan-Cancer cohort showed six genes [METTL1, METTL11B, EEF1AKNMT, METTL18, EEF1AKMT3 (METTL21B), RRNAD1 (METTL25B)] with high-level amplifications above 2%." (PMID 34285249, 2021).
tumor (2 papers, 2021 to 2024). "Quantified by ssGSEA in the HCC tumor environment, Spearman correlation has been applied to demonstrate the association between the immune cell infiltration level and the expression level of METTL18." (PMID 34123827, 2021). "Furthermore, we performed receiver operating characteristic (ROC), the area under the curve (AUC) of METTL18 is 0.948, which indicates that METTL18 was significantly different expression in tumor and normal tissue." (PMID 34123827, 2021). "In general, METTL18 is differentially expressed in tumor and normal samples." (PMID 34123827, 2021). "Besides, results have indicated that expression levels of METTL18 in 371 tumor tissues were higher than that in 160 normal samples (P < 0.001) and METTL18 expression in 248 tumor tissues was significantly increased compared with 220 normal samples (P < 0.001)." (PMID 34123827, 2021). "Again, METTL18 protein expression was higher in tumor tissue from HER2-negative patients but not in HER2-positive tumors." (PMID 39309445, 2024). "However, the impact of METTL18 in tumor development has not been explored." (PMID 34123827, 2021). "In contrast, CAMKMT and METTL18 both promoted tumor activity, but through different mechanisms: CAMKMT directly interacted with and likely methylated Src (detailed Src activation mechanisms by CAMKMT are currently being explored, data not shown), while METTL18 did not directly bind to Src." (PMID 39309445, 2024).
METTL18 also shares sentences with these, for which no sentence is quoted: melanoma (1 paper).